EZHIP (EZH inhibitory protein)
Description:
Inhibits PRC2/EED-EZH1 and PRC2/EED-EZH2 complex function by inhibiting EZH1/EZH2 methyltransferase activity, thereby causing down-regulation of histone H3 trimethylation on 'Lys-27' (H3K27me3). Probably inhibits methyltransferase activity by limiting the stimulatory effect of cofactors such as AEBP2 and JARID2. Inhibits H3K27me3 deposition during spermatogenesis and oogenesis (By similarity).
Synonyms: CXorf67; CATACOMB; KIP75
Tractability: No criterion of Open Targets' tractability assessment is met for any kind of drug.
Gene: Protein-coding gene on chromosome X (51,406,948 to 51,408,843, forward strand). Ensembl gene ENSG00000187690.
Subcellular location: Nucleus; Cytoplasm
Subcellular location (Human Protein Atlas): Nucleoplasm
Pathways (Reactome):
Gene expression (Transcription): PRC2 methylates histones and DNA
Gene Ontology:
Molecular function: histone methyltransferase inhibitor activity; protein binding
Biological process: chromatin organization; epigenetic regulation of gene expression
Cellular component: cytoplasm; cytosol; nucleoplasm; nucleus
Homologues: Orthologues: chimpanzee EZHIP (96% identical), macaque EZHIP (87% identical), dog EZHIP (49% identical), zebrafish si:ch211-221n20.7 (15% identical), zebrafish si:dkey-235d18.7 (14% identical), zebrafish si:ch211-14a11.1 (13% identical), zebrafish si:dkey-235d18.6 (11% identical), zebrafish si:ch211-221n20.2 (11% identical), zebrafish si:ch211-221n20.4 (11% identical), zebrafish si:ch211-14a11.2 (11% identical), zebrafish si:ch211-221n20.1 (11% identical).
Diseases named in the same sentence as EZHIP in open-access papers:
EZHIP is named in the same sentence as 28 diseases in open-access papers, as found by Europe PMC text mining. Sharing a sentence is not in itself a finding about the gene and the disease. The quoted sentences say what the papers report.
ependymoma (21 papers, 2018 to 2025). A WHO grade II, slow growing tumor of children and young adults, usually located intraventricularly. "Posterior fossa group A ependymomas (EPN_PFA) are characterized by a loss of H3 K27 trimethylation due to either EZHIP overexpression or H3 p.K27M mutation, similar to H3 K27-altered diffuse midline gliomas (DMG), but in reverse proportions." (PMID 36104744, 2022). "The H3K27M mutations in diffuse midline glioma (DMG) and EZHIP overexpression in ependymoma, while featuring increased levels of H3K27me3 at tumor suppressor genes such as CDKN2A, have broadly reduced levels of H3K27me3 and H3K27me2." (PMID 36105358, 2022). "After the first report of its mutation and overexpression in PFA ependymomas, increased attention sparked the start of the ongoing functional characterization of EZHIP not only in PFA, but also in ESS and germ cells." (PMID 34762160, 2022). "EZHIP variants occur in posterior fossa group A (PFA) ependymomas (9.4%), endometrial cancers (5%) and melanoma (2.6%)." (PMID 35456430, 2022). "While some PFA ependymomas contain the K27M mutation, EZHIP expression is the predominant mechanism for modulating PRC2 in these tumors." (PMID 31086175, 2019). "EZHIP missense mutations are found in 9.2% of PFA ependymomas and occur exclusively within a hotspot region in the poorly conserved N-terminus of the protein." (PMID 31086175, 2019). "However, until today it is unclear how the mutations in EZHIP affect the function of the protein or what their role is in ependymoma tumorigenesis." (PMID 34762160, 2022). "This initial hypothesis was further supported by later in-depth sequencing efforts on larger series of PFA ependymomas in which rare but recurrent mutations were identified in epigenetic proteins like enhancer of zeste inhibitory protein (EZHIP) and Histone H3 (H3)." (PMID 34762160, 2022). "Conversely, posterior fossa A (PFA) ependymoma are characterized by the oncogenic driver EZH inhibitory protein (EZHIP) and have the most dismal prognosis of all ependymoma subgroups." (PMID 40862786, 2025). "First, we observed increased expression of ACVR1 in PFAs compared to group B posterior fossa ependymomas (PFBs), a subtype of PF ependymomas that lacks EZHIP expression." (PMID 36759899, 2023). "EZHIP overexpression, resulting in H3K27me3 global reduction, has been first observed in posterior fossa type-A ependymomas." (PMID 36727064, 2022). "These include the H3K27M oncohistone mutation that occurs in diffuse midline gliomas, or expression of the gonad specific PRC2 subunit EZHIP in ependymoma." (PMID 36105358, 2022). "Due to this high specificity, EZHIP expression is discussed as a simple but reliable prognostic IHC biomarker for PFA ependymomas and EZHIP expressing DMGs." (PMID 34762160, 2022). "Instead, we and others identified EZHIP (previously known as CXorf67) as the main responsible protein for the diminished H3K27me3 levels in PFA ependymomas." (PMID 34762160, 2022). "We propose that aberrant expression of EZHIP contributes to PFA ependymoma tumorigenesis through dysregulation of PRC2-mediated gene repression." (PMID 31086175, 2019). "Interestingly, while there is global loss of H3K27me3-repressive marks in EZHIP-overexpressing tumors, this is accompanied by increased levels of H3K27me3 at the CDKN2A locus in PFA ependymomas expressing EZHIP." (PMID 38949020, 2024). "Future work will involve modeling these and other drivers of brainstem and forebrain pediatric brain tumors, such as alterations in EZHIP and FOXR2, which have been associated with hindbrain ependymomas and forebrain gliomas arising from similar progenitor niches as those targeted in this study." (PMID 37011011, 2023). "The few PFA ependymomas that do not overexpress EZHIP appeared to harbor K27M mutations in H3.1 or H3.3, which also inhibit EZH2." (PMID 37085539, 2023).
ependymoma (continued). "EZHIP is expressed in almost every PFA ependymoma, but not in cases that harbor the H3K27M mutation or in any of the other EPN groups." (PMID 34762160, 2022). "We speculate that PFA-ependymomas that express high levels of EZHIP will also exhibit differential sensitivity to EZH2 inhibitors." (PMID 31086175, 2019). "Such lower levels of H3K27me3 in PFA ependymomas are due to the overexpression of EZHIP (“enhancer of zeste homolog inhibitory protein”), a protein that might work as a potential tumor driver in PFA and that mimics K27M mutated histones, functioning as an intrinsic inhibitor of PRC2 function." (PMID 36727064, 2022). "Several reports described elevated EZHIP expression in DMG cases that lack H3 mutations, which supports the fact that EZHIP expression and H3K27M mutations are mutually exclusive and are encountered in reverse proportions: 3% versus 97% and 96% versus 4%, respectively, in DMG and PFA ependymomas." (PMID 36727064, 2022). "Posterior fossa type A (PFA) ependymomas exhibit very low H3K27 methylation and express high levels of EZHIP (Enhancer of Zeste Homologs Inhibitory Protein, also termed CXORF67)." (PMID 31086175, 2019). "In this study, we demonstrated that expression of EZHIP, a putative driver of PFA ependymomas, lowers global H3K27me3 levels through inhibition of PRC2 methyltransferase activity." (PMID 31086175, 2019). "Indeed, the EZH inhibitory protein (EZHIP, CXorf7) is overexpressed in some midline gliomas and posterior fossa type A ependymomas." (PMID 35875065, 2022). "PFA ependymomas show increased expression of Cxorf67/EZHIP and absence of H3K27me3." (PMID 34944845, 2021). "We next analyzed H3K27me3 ChIP and RNA sequencing data from supratentorial (EZHIP negative, high H3K27me3) and PFA ependymomas (EZHIP positive, low H3K27me3)." (PMID 31086175, 2019). "Moreover, aberrant Ezhip expression in PFA ependymomas has recently been shown to suppress homologous recombination-mediated DNA repair independent of the KLP motif, suggesting that EZHIP may modulate the DNA damage response." (PMID 41427323, 2025).
diffuse midline glioma (10 papers, 2022 to 2025). A diffuse glioma that arises from the midline structures of the central nervous system. "In the diffuse midline gliomas H3K27‐mutant/EZHIP overexpression subtype, the H3K27 mutation was confirmed in two out of four samples (CNS_019 and CNS_114), whereas CNS_065 tested negative and CNS_006 was not evaluated due to a lack of remaining material." (PMID 41033792, 2025). "Notably, recurrent mutations in EGFR and EZHIP have been implicated in PRC2 inhibition within a specific subgroup now classified under diffuse midline glioma with H3K27-alteration." (PMID 41050069, 2025). "Any glioma occurring in the midline must include diffuse midline glioma, H3K27-altered, in the differential diagnosis, and as such, H3K27me3, H3K27M and EZHIP IHC need to be included in the diagnostic panel." (PMID 39126064, 2024). "Some tumours initially classified as high‐grade glioblastomas or pilocytic astrocytomas were reclassified as diffuse midline glioma, H3K27‐altered, specifically of H3K27‐mutant or EZHIP‐overexpressing subtypes." (PMID 41033792, 2025). "H3K27-altered diffuse midline glioma (DMG) is a fatal disease, including four subtypes H3.3-mutant, H3.1/H3.2-mutant, H3-wildtype with EZHIP overexpression, and EGFR-mutant." (PMID 40849656, 2025).
glioma (8 papers, 2021 to 2025). A benign or malignant brain and spinal cord tumor that arises from glial cells (astrocytes, oligodendrocytes, ependymal cells). "For example, the current WHO classification now subsumes midline gliomas with H3 K27M mutations together with gliomas showing aberrant EZHIP expression or with an EGFR mutation." (PMID 40647406, 2025). "H3 wild-type glioma are characterized predominantly by the overexpression of the CXorf67 gene which encodes EZHIP." (PMID 35629262, 2022). "We conclude that EZHIP expression may be directly regulated by the methylation status of its promoter in gliomas." (PMID 36882456, 2023). "H3K27M-mutant gliomas will also have low EZHIP expression levels and will be negative for EZHIP IHC." (PMID 39126064, 2024). "Thalamic gliomas—mainly bilateral at the onset, showing EGFR variants, EZHIP (ex CXorf67) overexpression, and loss of H3.3K27me3 in the absence of H3F3A variants—have recently been described." (PMID 35456430, 2022).
endometrial stromal sarcoma (6 papers, 2019 to 2025). "One such fusion identified in endometrial stromal sarcomas occurred between motifs 8–10 of EZHIP and MBTD1, a chromatin reader of the NuA4 histone acetyltransferase complex." (PMID 41427323, 2025). "Elevated expression of EZHIP in tumors may be caused by mutations in cis-regulatory elements; the same effect may be conferred by the formation of fusion genes involving EZHIP locus (for instance, MBTD1–EZHIP fusion described for low-grade endometrial stromal sarcoma)." (PMID 34638438, 2021).
brain tumors (5 papers, 2021 to 2026). "Beyond brain tumors, EZHIP has emerged as an oncogenic driver in osteosarcoma, underscoring broader relevance across cancers." (PMID 41596609, 2026). "Following this, we evaluated expression levels of EZHIP as a marker of PFA EPN, using the ZERO cohort of high-risk pediatric brain tumors as a reference dataset." (PMID 36937401, 2023). "Loss of H3K27me3 has been shown in pediatric brain tumors and may be influenced by overexpression of the PRC2 inhibitory protein EZH Inhibitory Protein (EZHIP) and/or KDM6B, an H3K27me3 demethylase." (PMID 34399838, 2021). "In brain tumors, global loss of H3K27me3 may be explained by KDM6B over-expression, leading to H3K27me3 demethylation, and/or EZHIP over-expression that leads to inhibition of EZH2, resulting in global loss of H3K27me3." (PMID 34399838, 2021).
posterior fossa ependymoma (4 papers, 2020 to 2025). A high grade ependymoma that is located within the posterior fossa. "EZHIP was biologically mainly characterized by its mutation and overexpression in posterior fossa ependymoma." (PMID 37341056, 2023).
osteosarcoma (3 papers, 2019 to 2026). A usually aggressive malignant bone-forming mesenchymal neoplasm, predominantly affecting adolescents and young adults. "The EZHIP transcript is undetectable from most cell lines, with the exception of U2OS, an osteosarcoma-derived cell line." (PMID 31451685, 2019).
central neurocytoma (2 papers, 2024 to 2025). A benign brain tumor composed of neural elements which most often arise from the SEPTUM PELLUCIDUM and the walls of the lateral ventricles. "Recently, it was also reported that H3K27me3 loss could be found in central neurocytomas and pituicytomas, in the absence of H3F3A mutations and EZHIP overexpression." (PMID 39456545, 2024).
endometrial cancer (2 papers, 2019 to 2022). Primary or metastatic malignant neoplasm involving the endometrium (mucous membrane that lines the endometrial cavity). "Importantly, the MBTD1-CXORF67 fusion protein contains the C-terminus of EZHIP and the highly conserved H3 K27M-like sequence, suggesting that PRC2 inhibition and loss of H3K27 methylation may support tumorigenesis of this subtype of endometrial cancer." (PMID 31086175, 2019).
germ cell tumor (1 paper, 2022). A benign or malignant, gonadal or extragonadal neoplasm that originates from germ cells. "In the brain, PRC2 inhibition by either EZHIP or H3K27M leads to the de-repression of PLAG1 in PFA, DMG and germ cell tumors." (PMID 34762160, 2022). "In other CNS tumors, EZHIP is not expressed except for a small group of CNS germ cell tumors." (PMID 34762160, 2022).
medulloblastoma (1 paper, 2024). A malignant, invasive embryonal neoplasm arising from the cerebellum. "In addition, isolated cases of MYC methylation class AT/RT and WNT-activated medulloblastoma have been shown to present EZHIP positivity, but this was only focal (<1% of positive tumor cells), and thus, this was not to considered as true EZHIP overexpression (>90% of positive tumor cells)." (PMID 38544524, 2024).
posterior fossa ependymoma group (1 paper, 2025). "For example, loss of H3K27me3 is related to posterior fossa ependymoma group A, mainly through the expression of EZH inhibitory protein (EZHIP), and is associated with poor prognosis." (PMID 39636550, 2025).
tumor (14 papers, 2019 to 2026). "In TK-EPN862 and the matched patient tumor, we observed high expression of EZHIP RNA and protein, and the associated low levels of H3K27me3 detected via IHC, with a lack of histone gene mutations, consistent with a diagnosis of PFA EPN." (PMID 36937401, 2023). "One tumour harboured a FGFR1MUT in the context of a DMG H3-K27 wild-type with EZHIP overexpression presenting an ACVR1 mutation (case #60)." (PMID 38066305, 2023). "Furthermore, the H3-WT tumours with ACVR1 mutations had higher expression levels of EZHIP than H3-WT tumours with EGFR mutations." (PMID 36882456, 2023). "Concurrent with H3K27me3 loss, EZHIP is highly expressed in these tumours." (PMID 36882456, 2023). "Finally, we discuss therapeutic opportunities, from the direct targeting of intrinsically disordered proteins to the indirect modulation of EZHIP-associated epigenetic and metabolic landscapes, highlighting implications for tumor evolution and precision oncology." (PMID 41596609, 2026). "Around 95% of PFA tumours aberrantly express the EZHIP protein, which mimics the H3K27M oncohistone and potently inhibits PRC2, while H3K27M mutations are found in the remaining ~ 5% in a mutually exclusive manner." (PMID 40986124, 2025). "DNA methylation profiling can stratify H3K27 altered DMGs from other paediatric high-grade glioma, and can also distinguish between H3.1K27M and H3.3K27M tumour samples and EZHIP overexpressing and EGRF positive subtypes, suggesting a different cell of origin." (PMID 40986124, 2025). "We show that these tumours have recurrent and mutually exclusive mutations in either ACVR1 or EGFR and are characterised by high expression of EZHIP associated to its promoter hypomethylation." (PMID 36882456, 2023). "Although we report a trend for H3-WT ACVR1-mutant tumours to express higher levels of EZHIP, our cohort size is too small for this observation to reach statistical significance and a larger cohort would be required to confirm our findings." (PMID 36882456, 2023). "We confirmed the overexpression of EZHIP by immunohistochemistry in the four tumours for which FFPE tissue was available." (PMID 36882456, 2023). "This entity, however, was excluded by absence of H3K28M (H2K27M) mutation, EZHIP overexpression, and retained H3K28me3 expression and does not usually display the solid growth pattern of the tumor assessed here." (PMID 38345610, 2024). "We describe for the first time in H3-WT DMG similar findings, and we further hypothesise that dysregulation of EZHIP via promoter demethylation could be occurring as an early event in these tumours." (PMID 36882456, 2023). "Interestingly, in this subgroup, H3-WT tumours express high levels of EZH Inhibitory Protein (EZHIP) previously known as CXorf676,8,9." (PMID 36882456, 2023). "The identification of EZHIP as a potential tumor driver in PFA spiked a lot of interest and was quickly followed up by intense research into its mechanism of action, sparking hope to finally find answers to all the open questions and challenges in PFA research and patient care." (PMID 34762160, 2022). "We found that missense mutations do not affect the H3K27 methylation lowering activity of EZHIP in vivo, suggesting that these tumor mutations do not alter the EZHIP protein function." (PMID 31086175, 2019). "Further studies are required to know whether EZHIP upregulation might be a recurrent event in cancers and act as a driver of tumor progression." (PMID 31451685, 2019). "PFA tumours express high levels of EZHIP (also known as CXORF67)." (PMID 31086175, 2019). "In all tumours where EZHIP was expressed, the probe cg20931907 (chrX:51149742), and to a lesser extent probes cg11132751 and cg14505980, were unmethylated, in keeping with the hypothesis that the methylation of CpG islands within the EZHIP promoter represses gene expression." (PMID 36882456, 2023).
tumor (continued). "In this regard, the cell of origin in other H3K27a DMG tumours remains elusive, with no current models of EZHIP-DMG for disease modelling in this context posing further research questions." (PMID 40986124, 2025). "However, one H3-WT tumour without EZHIP overexpression (zcc446) was aneuploid with a high density of single nucleotide and structural variants and lacking either ACVR1 or EGFR mutations." (PMID 36882456, 2023). "Until today, it is not clear whether EZHIP is naturally expressed during PFA tumor initiation in the cell of origin or becomes activated in the process of tumorigenesis." (PMID 34762160, 2022). "Of note, H3K27M DMG tumours did not display a TULIP-like chromatin architecture, suggesting that EZHIP’s capacity to generate TULIPs may not stem solely from PRC2 inhibition but could depend on the specific epigenetic state of the cell of origin or the developmental timing unique to PFA." (PMID 40986124, 2025).